GORASP2 (golgi reassembly stacking protein 2)
Description:
Key structural protein of the Golgi apparatus. The membrane cisternae of the Golgi apparatus adhere to each other to form stacks, which are aligned side by side to form the Golgi ribbon. Acting in concert with GORASP1/GRASP65, is required for the formation and maintenance of the Golgi ribbon, and may be dispensable for the formation of stacks. However, other studies suggest that GORASP2 plays a role in the assembly and membrane stacking of the Golgi cisternae, and in the process by which Golgi stacks reform after breakdown during mitosis and meiosis. May regulate the intracellular transport and presentation of a defined set of transmembrane proteins, such as transmembrane TGFA. Required for normal acrosome formation during spermiogenesis and normal male fertility, probably by promoting colocalization of JAM2 and JAM3 at contact sites between germ cells and Sertoli cells (By similarity). Mediates ER stress-induced unconventional (ER/Golgi-independent) trafficking of core-glycosylated CFTR to cell membrane.
Synonyms: GRS2; GOLPH6; GRASP55; p59
Tractability: Small molecule: it has a high-quality binding pocket. PROTAC: ubiquitination databases record sites on it; its protein half-life has been measured.
Gene: Protein-coding gene on chromosome 2 (170,928,464 to 170,967,135, forward strand). Ensembl gene ENSG00000115806.
Subcellular location: Golgi apparatus membrane; Endoplasmic reticulum membrane; Golgi apparatus
Subcellular location (Human Protein Atlas): Golgi apparatus
Pathways (Reactome):
Cell Cycle: Golgi Cisternae Pericentriolar Stack Reorganization
Gene Ontology:
Molecular function: protein binding
Biological process: establishment of protein localization to plasma membrane; organelle assembly; organelle organization; response to endoplasmic reticulum stress; Golgi organization
Cellular component: endoplasmic reticulum membrane; Golgi apparatus; Golgi membrane; cis-Golgi network; membrane
Genetic constraint (gnomAD): Loss-of-function variants: 6 observed, 16.35 expected, observed/expected ratio (o/e) 0.37, 90% interval 0.2 to 0.72. The upper end of that interval is the gene's LOEUF score, 0.72, which puts it in group 2 of 6, group 1 being the genes least tolerant of losing a copy. Missense variants: 286 observed, 331.83 expected, observed/expected ratio (o/e) 0.86, 90% interval 0.78 to 0.95. Synonymous variants: 149 observed, 139.83 expected, observed/expected ratio (o/e) 1.07, 90% interval 0.93 to 1.22.
Homologues: Orthologues: chimpanzee GORASP2 (99% identical), macaque GORASP2 (98% identical), rabbit GORASP2 (92% identical), pig GORASP2 (92% identical), dog GORASP2 (91% identical), mouse Gorasp2 (90% identical), rat Gorasp2 (90% identical), guinea pig GORASP2 (88% identical), tropical clawed frog gorasp2 (67% identical), zebrafish gorasp2 (66% identical), Drosophila melanogaster Grasp65 (44% identical), Caenorhabditis elegans Y42H9AR.1 (40% identical). Paralogues in human: GORASP1 (39% identical).
Diseases named in the same sentence as GORASP2 in open-access papers:
GORASP2 is named in the same sentence as 26 diseases in open-access papers, as found by Europe PMC text mining. Sharing a sentence is not in itself a finding about the gene and the disease. The quoted sentences say what the papers report.
lung adenocarcinoma (2 papers, 2019 to 2025). A carcinoma that arises from the lung and is characterized by the presence of malignant glandular epithelial cells. "Since DNA demethylation-triggered overexpression of SFN has essential functions during the course of lung adenocarcinoma progression, we expect that GORASP2 and ZYG11A might also have some functional association in this tumor." (PMID 30899432, 2019). "Multivariate analysis also indicated that lymphatic permeation, vascular invasion, pathological stage, and expression of GORASP2 or ZYG11A were independent prognostic factors indicative of poor survival in patients with lung adenocarcinoma." (PMID 30899432, 2019). "GORASP2 showed significantly higher expression in invasive lung adenocarcinoma (76/123 cases, 61%) than in non-invasive lung adenocarcinomas (2/48 cases, 4%)." (PMID 30899432, 2019). "Next, to investigate the expression pattern and clinicopathological implications of SFN, GORASP2 and ZYG11A, we performed IHC using 171 cases of lung adenocarcinoma." (PMID 30899432, 2019).
HIV-1 infection (1 paper, 2015). The type species of lentivirus and the etiologic agent of acquired immunodeficiency syndrome (AIDS). "GORASP2 was found to regulate HIV-1 infection, as it was one of 37 genes that decreased MAGI cell β-galactosidase reporter activity at least 2-fold for at least three out of four siRNAs in a study of HIV-responsive phosphoproteins." (PMID 25884674, 2015).
infertile (1 paper, 2017). "Male Gorasp2-/- mice bred normally (mating behaviors, plug production), but these mice were infertile." (PMID 28617811, 2017).
male infertility (1 paper, 2017). The inability of the male to effect fertilization of an ovum after a specified period of unprotected intercourse. "Gorasp2-/- mice display male infertility but do not present other gross morphological defects, similarly to Jam3-deficient mice." (PMID 28617811, 2017).
tumor (4 papers, 2019 to 2024). "Similarly, inhibition of GORASP2 might disrupt the membrane dynamics of the Golgi apparatus, thus leading to a substantial anti-tumor effect." (PMID 30899432, 2019). "Despite this, we identified 2 new genes, GORASP2 and ZYG11A, which show hypomethylation and overexpression in invasive adenocarcinoma, suggesting that they have important functions in tumor cells." (PMID 30899432, 2019). "Despite DNA demethylation at the promoter region might be rare relative to DNA hypermethylation, we identified 2 new genes, GORASP2 and ZYG11A, which show hypomethylation and overexpression in invasive adenocarcinoma, suggesting that they have important functions in tumor cells." (PMID 30899432, 2019).
GORASP2 also shares sentences with these, for which no sentence is quoted: cancer (4 papers); infection (4); lung carcinoma (2); Alzheimer disease (1); autism spectrum disorder (1); colon cancer (1); colorectal cancer (1); cystic fibrosis (1); endometrial cancer (1); HCMV infection (1); Huntington disease (1); ischemic stroke (1); Legionella infection (1); leukemia (1); neuroblastoma (1); neurodegenerative disease (1); Obesity (1); ovarian tumour (1); Stroke (1); type 1 diabetes (1); viral infection (1).